SERPINA3 (serpin family A member 3)
Diseases named in the same sentence as SERPINA3 in open-access papers (continued):
Sharing a sentence is not in itself a finding about the gene and the disease.
prion disease (8 papers, 2014 to 2024). A transmissible disease that is caused by a protein that is able to induce abnormal folding of normal cellular proteins, leading to characteristic spongiform brain changes, which are associated with neuronal loss without an inflammatory response. "Several hypotheses considering the pathogenic effects of SERPINA3 overexpression in prion diseases have been proposed—e.g., that it may contribute to PrPSc formation or hamper PrPSc clearance." (PMID 33375642, 2020). "Additional studies in other readily accessible tissues such as CSF and urine may be needed to address the diagnostic potential of SERPINA3 mRNA detection in both preclinical and clinical stages of human prion diseases." (PMID 29142239, 2017). "Western blot (WB) and RT-qPCR analysis of human frontal cortex specimens from patients affected by other types of prion diseases confirmed elevated levels of SERPINA3." (PMID 35416570, 2022). "The SERPINA3/SerpinA3nincreased anti-protease activity found in post-mortem brain tissue of AD and prion disease samples suggest its involvement in the neurodegenerative processes." (PMID 35416570, 2022). "SERPINA3 overexpression has previously been reported in the frontal and occipital cortices of various human prion diseases." (PMID 33375642, 2020). "Nevertheless, other forms of prion disease show significant up-regulation of the SERPINA3 transcript, ranging from 30 to 40 folds in all groups considered." (PMID 29142239, 2017). "We report SERPINA3 to be strongly up-regulated in the brain of all human prion diseases, with only a mild up-regulation in AD." (PMID 29142239, 2017). "In this work we provide evidence for strong up-regulation of SERPINA3 mRNA in the CNS of patients deceased from different forms of prion diseases." (PMID 29142239, 2017). "Immunohistochemistry and biochemical analyses for SERPINA3 protein were also performed, confirming the specific and differential up-regulation of the protein in sporadic, genetic or acquired forms of prion disease." (PMID 29142239, 2017). "As for GFAP, we found a similar dysregulation pattern as for SERPINA3 among all groups, up-regulation in all prion diseases together with a negligible increase in AD samples." (PMID 29142239, 2017). "The elevated and specific up-regulation of SERPINA3 mRNA in human brain samples of prion diseases offers the possibility of using this transcript as a new tool to help distinguish different forms of these disorders." (PMID 29142239, 2017). "Among the different prion diseases, there was striking up-regulation of SERPINA3 mRNA in iCJD specimens, up to about 350 fold." (PMID 29142239, 2017). "SERPINA3 was found to be strongly up-regulated in all prion diseases: sCJD (FC = 40.3), vCJD (FC = 38.8), FFI (FC = 52.7), gCJD (FC = 39.1) and GSS (FC = 12.17, not significant) cases." (PMID 29142239, 2017). "In prion disease studies, SERPINA3 was found increased in brains of scrapie-infected mice, in mice infected with RML prior to clinical onset as well as in urine and cerebrospinal fluid of CJD patients." (PMID 24898206, 2014). "Our analysis revealed that, besides the already observed upregulation of SERPINA3 in patients with prion disease and AD, SERPINB1, SERPINB6, SERPING1, SERPINH1, and SERPINI1 were dysregulated in sCJD individuals compared to controls, while only SERPINB1 was upregulated in AD patients." (PMID 35416570, 2022). "Starting from the recent discovery of SERPINA3/SerpinA3n upregulationduring prion diseases, we have identified a small molecule, namedcompound 5 (ARN1468), inhibiting the function of these serpins andeffectively reducing prion load in chronically infected cells." (PMID 35771181, 2022). "In this context, the SERPINA3 proteincould play a role in prion disease pathogenesis." (PMID 35771181, 2022). "However, among all the members of the serpin superfamily, SERPINA3/SerpinA3n was the only gene upregulated in prion disease and AD in both human samples and mouse models." (PMID 35416570, 2022).
prion disease (continued). "We found strong up-regulation in the gene expression of SERPINA3 in all prion diseases considered." (PMID 29142239, 2017). "Understanding the molecular mechanism for SERPINA3 up-regulation in prion diseases may shed light to the cellular events that regulates prion conversion, replication and accumulation." (PMID 29142239, 2017). "Our data suggest that SERPINA3 may be involved in the pathogenesis and the progression of prion diseases, representing a valid tool for distinguishing different forms of these disorders in humans." (PMID 29142239, 2017). "How SERPINA3 is up-regulated in prion diseases remains to be established." (PMID 29142239, 2017). "As for SERPINA3, GFAP was up-regulated in all prion diseases, with the highest value observed in gCJD patients (FC = 5.2) and iCJD (FC = 5), sCJD (FC = 3), GSS (FC = 2.9, not significant) vCJD (FC = 2.8) and FFI (FC = 2.2)." (PMID 29142239, 2017).
prostate carcinoma (8 papers, 2013 to 2025). A carcinoma that arises from epithelial cells of the prostate gland. "In this study, we investigated whether the expression of SERPINA3 in prostate cancer cells is associated with the progression of CRPC." (PMID 40367014, 2025). "Through bioinformatics analysis and both in vitro experiments, we confirmed that SERPINA3 can significantly inhibit the progression of prostate cancer." (PMID 40367014, 2025). "In prostate cancer, SERPINA3 promotes aerobic glycolysis and autophagy while inhibiting apoptosis of cancer cells." (PMID 36406134, 2022). "We assessed the levels of urinary EV-associated proteins based on 40 samples consisting of 20 cases and 20 controls, where 18 EV proteins were identified to be differentiated in prostate cancer outcome, of which three (i.e., SERPINA3, LRG1, and SCGB3A1) were shown to be consistently upregulated." (PMID 36500247, 2022). "In addition, SERPINA3 has been identified to be upregulated in sera from thyroid papillary carcinoma and prostate cancers." (PMID 24179540, 2013). "Therefore, we will further analyze the infiltration levels of M1 macrophages in tumor tissues to determine whether SERPINA3 inhibits the progression of prostate cancer by promoting the increased infiltration of M1 macrophages into the tumor microenvironment." (PMID 40367014, 2025). "The authors show that SERPINA3 and LCN2 have osteogenic and tumor‐suppressive roles at sites of bone metastases in osteoblastic prostate cancer." (PMID 37408474, 2023). "The clustering yielded a clear pattern of the five upregulated EV proteins (i.e., SERPINA3, SCGB3A1, LRG1, SERPINA6, and CP) enriched in the prostate cancer cases." (PMID 36500247, 2022). "In comparison to the discovery cohort, the identified EV proteins (i.e., SERPINA3, LRG1, and SCGB3A1) gained from the validation cohort clearly complied with the discovery cohort, which indicated the effect of the identified EV proteins on prostate cancer were stable." (PMID 36500247, 2022). "Mechanistically, we found that SERPINA3 may influence the expression of CXCL2 to activate the IL-17 and TNFα signaling pathways, thereby mediating the recruitment of M1 macrophages in the tumor microenvironment and exerting an inhibitory effect on prostate cancer progression." (PMID 40367014, 2025). "In a co‐culture of osteoblasts (OBs) and BPCa cells, SERPINA3 and LCN2 were remarkably upregulated in BPCa via OB‐derived extracellular vesicles, while they were not in the co‐culture of OBs and osteolytic prostate cancer (LPCa) cells." (PMID 37408474, 2023). "We observed several EV proteins, particularly SERPINA3, LRG1, and SCGB3A1, which showed a consistent difference between prostate cancer cases and non-prostate cancer controls across three DIA methods, which could be suggested as potential biomarkers and deserve further verification." (PMID 36500247, 2022).
asthma (6 papers, 2015 to 2025). "An association between childhood onset asthma and a 1.4 kb gain mutation downstream of SERPINA3 has been reported." (PMID 33072128, 2020). "In one such study in which findings from the next gen proteomics approach was validated by enzyme-linked immunosorbent assay (ELISA), SERPINA3 was found to be higher in patients with asthma and was particularly higher in patients with an acute exacerbation of their asthma." (PMID 38057814, 2023). "Recently, SERPINA3 was identified to be higher in severe asthma patients compared to mild asthma patients and healthy controls." (PMID 40606296, 2025).
cognitive decline (6 papers, 2021 to 2025). "The increase in urinary SERPINA3 preceding cognitive decline observed in the present study is consistent with the findings of these previous studies." (PMID 37006491, 2023). "SERPINA3 is speculated to have a role in cognitive decline, although the exact mechanism has not yet been clarified." (PMID 40471493, 2025).
dementia (6 papers, 2004 to 2023). Loss of intellectual abilities interfering with an individual's social and occupational functions. "For example, high levels of α1-antichymotrypsin (the protein product of SERPINA3) in blood plasma have been associated with increased risk for dementia." (PMID 23705665, 2013).
liver cancer (6 papers, 2021 to 2025). An epithelial or non-epithelial malignant neoplasm that arises from the liver. "Reduced SERPINA3 levels in serum are associated with poor survival in patients with liver cancer, and it has been proposed as a biomarker for disease diagnosis and prognosis." (PMID 40744994, 2025). "It has been found that the expression level of SerpinA3 decreases in the progression of liver cancer, and overexpression of SerpinA3 can inhibit the proliferation of liver cancer cells." (PMID 37288300, 2023). "While in liver cancer, in which SERPINA3 relatively highly localized in nuclei, this protein indicates a better patient survival." (PMID 37414914, 2023). "And one study has pointed that SerpinA3 can inhibit the development and metastasis of liver cancer by targeting PTEN/PI3K/AKT/mTOR signal pathway." (PMID 37288300, 2023). "The results showed that the expression of PAIP1 had a significant negative correlation (P < 0.05) with that of APOC3, CCL14, IL1RN, SERPINA3, and HAMP in liver cancer tissues." (PMID 37101794, 2023).
lung carcinoma (6 papers, 2014 to 2026). "The proteins related to host defense, CRP, C9 and SERPINA3, are elevated in lung cancer and may arise from tumor-induced stromal inflammation." (PMID 25114662, 2014).
Obesity (6 papers, 2017 to 2025). Accumulation of substantial excess body fat. "However, most studies focusing on SerpinA3, to date have been conducted in models of retinal and corneal damage, leaving the specific role of SerpinA3k in the context of diabetes and obesity largely unexplored." (PMID 41329353, 2025). "Furthermore, we have previously demonstrated that urinary SerpinA3 serves as an early biomarker of kidney damage, including diabetic nephropathy; however, its functional role in renal damage, obesity, and T2D remains largely unexplored." (PMID 41329353, 2025). "Because human SerpinA3 can also inhibit Cathepsin G, whether SerpinA3 can inhibit chronic adipose inflammation to ameliorate obesity and metabolic disorders by targeting Cathepsin G in humans merits further investigation." (PMID 37288300, 2023).
ovarian cancer (6 papers, 2010 to 2024). A primary or metastatic malignant neoplasm involving the ovary. "Previously, studies have shown that upregulation of SERPINA3 expression was an index of worse prognosis in ovarian cancer than low SERPINA3 level." (PMID 31998645, 2019).
Stroke (6 papers, 2008 to 2025). Sudden impairment of blood flow to a part of the brain due to occlusion or rupture of an artery to the brain. "In fact, PTX3 surpasses SERPINA3 and hsCRP, in that order, as a long-term prognostic marker of the endpoint consisting of all-cause mortality or MI or stroke in men." (PMID 39897419, 2025). "Our study results indicate that both SERPINA3 and hsCRP also may serve as long-term predictors of a composite endpoint consisting of all-cause mortality or MI or stroke in men admitted to hospital with chest pain of suspected coronary origin." (PMID 39897419, 2025). "Plasma SERPINA3 levels peak at approximately 36 hours after admission and then declined to a relatively lower level until day 3 post-stroke." (PMID 40157917, 2025). "On the other hand, existing data showed an increased expression of SERPINA3 in atherosclerotic lesions from a minor stroke and TIA, and SERPINA3 mRNA level was higher in plaque aorta of Apoe−/− mice than in plaque-free aorta of control mice." (PMID 34957248, 2021). "Plasma analysis of 250 ICH patients and 250 healthy controls revealed significantly higher SERPINA3 levels in ICH patients, correlating with hemorrhage severity, National Institutes of Health Stroke Scale (NIHSS), and Glasgow Coma Scale (GCS) scores, and long-term functional outcomes." (PMID 40157917, 2025). "SERPINA3 was positively correlated with ABC/2 scores (P < 0.001) and NIHSS scores (P < 0.001) and negatively correlated with GCS scores (P < 0.001) after adjusting for the time between stroke onset and blood collection, as well as other potential confounding factors (all P < 0.001)." (PMID 40157917, 2025).
type 2 diabetes (6 papers, 2019 to 2025). "This change was also confirmed to be increased in T2D patients, indicating SERPINA3 could be used for the early detection of type 2 diabetes mellitus." (PMID 35252405, 2022).
preeclampsia (5 papers, 2022 to 2025). Preeclampsia is a hypertensive disorder of pregnancy that is characterized by new-onset hypertension with proteinuria presenting after 20 weeks of gestation, and depending on mild or severe forms may initially present with severe headache, visual disturbances, and hyperreflexia. "The SERPINA3 gene is identified as a key diagnostic biomarker for preeclampsia, showing differential expression in affected placentas and associations with immune cell infiltration." (PMID 40357364, 2025). "COL17A1, FLT1, FSTL3, and SERPINA3 were identified as diagnostic genes of preeclampsia and validated in the GSE44711 datasets." (PMID 35528613, 2022). "Our study identified COL17A1, FLT1, FSTL3, and SERPINA3 as novel diagnostic biomarkers for preeclampsia patients." (PMID 35528613, 2022). "SERPINA3 demonstrated the highest preeclampsia expression compared to accreta in our microarray analysis, but while it has been shown to be upregulated in placentas complicated by preeclampsia, its function is paradoxically to promote cell invasion." (PMID 41141914, 2025). "miR-34a is highly expressed in the adult mammalian brain; it is a tumour suppressor, a regulator of endothelial and mitochondrial function, a modulator of NF-κB signalling pathway for T cell function, and appears to function as a negative regulator of SERPINA3 in preeclampsia." (PMID 40407536, 2025). "Our findings together with previous findings suggested COL17A1, FLT1, FSTL3, and SERPINA3 may influence the immune function of preeclampsia patients." (PMID 35528613, 2022). "Since SERPINA3 is induced under hypoxic conditions, its upregulation may be a marker of low oxygen conditions in the late trimester preeclampsia placenta as opposed to serving as a cause of disease pathogenesis." (PMID 41141914, 2025). "The distinct upregulation of COL17A1, SERPINA3, FSTL3, and FLT1 in preeclampsia was further demonstrated." (PMID 35528613, 2022).
triple-negative breast carcinoma (5 papers, 2021 to 2025). An invasive breast carcinoma which is negative for expression of estrogen receptor (ER), progesterone receptor (PR), and human epidermal growth factor receptor 2 (HER2). "SERPINA3 has been linked to increased tumour aggression, with an increase in tumour migration and invasion in triple negative breast cancer and worse prognosis associated to higher SERPINA3 values." (PMID 40087712, 2025). "SERPINA3 values in tissue correlated with poor prognosis in triple negative breast cancer and were predictive for reduced efficacy of cisplatin chemotherapy." (PMID 40087712, 2025). "GIG25 is a serpin family A member 3 (or SERPINA3), and overexpression of SERPINA3 promotes tumor invasion and migration, and epithelial–mesenchymal transition in triple-negative breast cancer cells." (PMID 37511481, 2023). "With strong aggressive abilities, triple-negative breast cancer (TNBC) cell lines (MDA-MB-231, BT549 and MDA-MB-436) were obtained to examine SERPINA3 expression and functions." (PMID 33569740, 2021).
chronic obstructive pulmonary disease (4 papers, 2010 to 2022). A chronic and progressive lung disorder characterized by the loss of elasticity of the bronchial tree and the air sacs, destruction of the air sacs wall, thickening of the bronchial wall, and mucous accumulation in the bronchial tree. "The SERPINA1, SERPINA3, and SERPINE2 genes, which encode antiproteases, have been proposed to be susceptible genes for of chronic obstructive pulmonary disease (COPD) and related phenotypes." (PMID 21067581, 2010).
delirium (4 papers, 2018 to 2022). A disorder characterized by confusion; inattentiveness; disorientation; illusions; hallucinations; agitation; and in some instances autonomic nervous system overactivity. "Finally, AZGP1, MMP-9, neopterin, phenylalanine–tyrosine ratio, SERPINA3, thioredoxin, and 8-iso-prostaglandin F2α were linked to postoperative delirium." (PMID 31263968, 2019).
endothelial dysfunction (4 papers, 2021 to 2025). In vascular diseases, endothelial dysfunction is a systemic pathological state of the endothelium (the inner lining of blood vessels) and can be broadly defined as an imbalance between vasodilating and vasoconstricting substances produced by (or acting on) the endothelium. "From the 14 upregulated exosomal proteins, FBG, FGG, ITIH4, and SERPINA3 coding gene for alpha-1-antichymotrypsin were associated to endothelial dysfunction and coagulation cascade activation and platelet degranulation." (PMID 33535467, 2021). "In summary, among four inflammatory biomarkers that we investigated, SERPINA3 level at baseline was associated with WMH severity, which revealed a novel biomarker for CSVD and validated its relationship with inflammation and endothelial dysfunction." (PMID 37721405, 2024).
influenza (4 papers, 2023 to 2026). An acute viral infection of the respiratory tract, occurring in isolated cases, in epidemics, or in pandemics; it is caused by serologically different strains of viruses (influenzaviruses) designated A, B, and C, has a 3-day incubation period, and usually lasts for 3 to 10 days. "The results showed that in influenza, high expression of SERPINA3, SAA1, and SAA2 was associated with a higher risk." (PMID 40158620, 2026). "In influenza, high expression of SERPINA3, SAA1, and SAA2 is associated with higher risk." (PMID 40158620, 2026). "Compared with those of the influenza group, the salivary samples of children with Streptococcus pneumoniae infection had significantly higher SERPINA3 levels." (PMID 37189569, 2023). "SERPINA3 is also an inflammatory cytokine gene, which could induce significant lung injury after influenza infection." (PMID 36650470, 2023). "LBP and SERPINA3 were mainly elevated in lung damage induced by influenza and non‐COVID‐19 DAD." (PMID 37519267, 2023).